RBMS2 (RNA binding motif single stranded interacting protein 2)
Synonyms: SCR3
Tractability: PROTAC: ubiquitination databases record sites on it.
Gene: Protein-coding gene on chromosome 12 (56,521,820 to 56,596,193, forward strand). Ensembl gene ENSG00000076067.
Subcellular location: Nucleus
Subcellular location (Human Protein Atlas): Nucleoli fibrillar center; Cytosol; Nucleoplasm
Gene Ontology:
Molecular function: RNA binding; mRNA 3'-UTR binding; poly(U) RNA binding; nucleic acid binding
Biological process: RNA processing
Cellular component: cytosol; nucleus; ribonucleoprotein complex
Genetic constraint (gnomAD): Loss-of-function variants: 37 observed, 55.84 expected, observed/expected ratio (o/e) 0.66, 90% interval 0.51 to 0.87. The upper end of that interval is the gene's LOEUF score, 0.87, which puts it in group 3 of 6, group 1 being the genes least tolerant of losing a copy. Missense variants: 364 observed, 491.34 expected, observed/expected ratio (o/e) 0.74, 90% interval 0.68 to 0.81. Synonymous variants: 151 observed, 175.99 expected, observed/expected ratio (o/e) 0.86, 90% interval 0.75 to 0.98.
Homologues: Orthologues: chimpanzee RBMS2 (99% identical), macaque RBMS2 (99% identical), dog RBMS2 (93% identical), guinea pig RBMS2 (93% identical), rabbit RBMS2 (92% identical), pig RBMS2 (91% identical), rat Rbms2 (84% identical), mouse Rbms2 (84% identical), tropical clawed frog rbms2 (78% identical), zebrafish rbms2a (73% identical), zebrafish rbms2b (72% identical). Paralogues in human: RBMS1 (67% identical), RBMS3 (67% identical), PABPC1 (27% identical), PABPC3 (26% identical), PABPC1L (25% identical), ELAVL2 (25% identical), PABPC4 (25% identical), ELAVL4 (25% identical), PUF60 (24% identical), ELAVL3 (23% identical), ELAVL1 (22% identical), HNRNPR (22% identical), and 12 more.
Diseases named in the same sentence as RBMS2 in open-access papers:
RBMS2 is named in the same sentence as 11 diseases in open-access papers, as found by Europe PMC text mining. Sharing a sentence is not in itself a finding about the gene and the disease. The quoted sentences say what the papers report.
breast carcinoma (7 papers, 2018 to 2024). "Downregulation of RBMS2 has been implicated in the pathogenesis and progression of various cancers, such as lung cancer and breast cancer." (PMID 38058408, 2023). "Considering the few studies on RBMS2, further research will be conducted in other types of breast cancer." (PMID 35280673, 2022). "Summarily, our study reveals a novel mechanism for RBMS2 as a regulator of chemotherapy response to DOX in breast cancer." (PMID 35280673, 2022). "Then, we discovered that BMF expression was downregulated and positively correlated with RBMS2 expression in breast cancer and normal tissues from our hospital and TCGA databases." (PMID 35280673, 2022). "RBMS2 acted as a tumor suppressor and has relatively low expression in breast cancer, resulting in the minor knockdown effects." (PMID 35280673, 2022). "Overexpression of RBMS2 robustly strengthened DOX-induced apoptosis in breast cancer cells, while inhibition of RBMS2 abated DOX-induced apoptosis." (PMID 35280673, 2022). "After DOX treatment, the ability of RBMS2 overexpressed breast cancer cells to form colonies was much worse than that of control cells, while inhibition of RBMS2 impaired the proliferation of breast cancer to a much lesser extent." (PMID 35280673, 2022). "This understanding of RBMS2 in breast cancer proliferation will help in the development of new breast cancer therapeutic approaches." (PMID 30514345, 2018). "Overexpression of RBMS2 inhibited the proliferation breast cancer while knockdown of RBMS2 promoted it both in vivo and in vitro." (PMID 30514345, 2018). "In the present study, the role of RBMS2 was studied in breast cancer and we found that it acted as a novel tumor suppressor by stabilizing P21 mRNA in breast cancer." (PMID 30514345, 2018). "The tumor sizes of breast cancers that have high expression of RBMS2 are smaller than that of those who have low expression." (PMID 30514345, 2018). "RBMS2 was found to be downregulated in breast cancer both from TCGA databases analysis and the patients’ samples from our hospital." (PMID 30514345, 2018). "So we can’t prove that RBMS2 functions through c-MYC in breast cancer and more experiments are needed to prove it." (PMID 30514345, 2018). "The effect of RBMS2 on breast cancer proliferation was evaluated in vitro using CCK-8 assays, colony formation assays and cell-cycle assays and the in vivo effect was investigated using a mouse tumorigenicity model." (PMID 30514345, 2018). "IHC from the Human Protein Atlas database confirmed the lower expression of RBMS2 in breast cancer in protein level." (PMID 30514345, 2018). "In conclusion, RBMS2 acted as a tumor suppressor in breast cancer and positively regulated the expression of P21 by stabilizing its mRNA." (PMID 30514345, 2018). "We further confirmed that RBMS2 was expressed lower in breast cancer tissues than adjacent normal tissues of patients in our hospital." (PMID 30514345, 2018). "The expression of RBMS2 was also lower in breast cancer cells compared to normal breast cell line (MCF-10A) both in mRNA and in protein." (PMID 30514345, 2018). "The expression of RBMS2 was lower in breast cancer compared with normal tissues and was a favorable biomarker in breast cancer." (PMID 30514345, 2018). "KM plot was further used to explore the relationship of RBMS2 expression with survival of breast cancer patients." (PMID 30514345, 2018). "RBMS2 as a member of RBM family acts as a tumor suppressor in breast cancer and our study highlighted the role of inhibiting tumor proliferation." (PMID 30514345, 2018). "Indeed, RBMS2 was reported to chemosensitize breast cancer cells to doxorubicin, implying its therapeutic potential." (PMID 38058408, 2023). "In particular, cleaved caspase 3 and cleaved caspase 9 were more significantly upregulated than caspase 3 and caspase 9, indicating that RBMS2 could induce breast cancer cells apoptosis." (PMID 35280673, 2022). "Collectively, RBMS2 sensitized breast cancer cells to DOX in vitro." (PMID 35280673, 2022).
breast carcinoma (continued). "Our data demonstrated that upregulation of RBMS2 in breast cancer cells could enhance sensitivity to doxorubicin and promote apoptosis in the presence of doxorubicin, while inhibition of RBMS2 showed an opposite trend." (PMID 35280673, 2022). "In this study, we found that overexpression of RBMS2 could improve DOX sensitivity and induce apoptosis in breast cancer cells, while inhibition of RBMS2 showed an opposite effect." (PMID 35280673, 2022). "Further animal experiments confirmed the sensibilization to DOX of RBMS2 in breast cancer cells." (PMID 35280673, 2022). "RBMS2 was proved to inhibit the proliferation of breast cancer." (PMID 30514345, 2018). "RBMS2 was significantly down expressed in breast cancer with log (foldchange) -1.21 and FDR < 0.05." (PMID 30514345, 2018). "In TCGA database, P21 and RBMS2 mRNA was also positively correlated in breast cancer petients." (PMID 30514345, 2018). "RBMS2 inhibited the proliferation of breast cancer and P21 was the main target of RBMS2." (PMID 30514345, 2018). "In our study, we identified RBMS2 as a tumor suppressor in breast cancer." (PMID 30514345, 2018). "Moreover, we analyzed the correlation between the expression of RBMS2 and clinicopathological characteristics of breast cancers in 80 patients." (PMID 30514345, 2018). "In our study, RBMS2 positively regulated the expression of P21 and anti-proliferation activity induced by overexpression of RBMS2 was rescued by interfering the expression of P21, which indicates P21 was a main target of RBMS2 in its promoting its anti-proliferation activity in breast cancer." (PMID 30514345, 2018). "Activating RBMS2 expression may represent a novel strategy for drug-resistant breast cancer." (PMID 35280673, 2022). "In summary, BMF could rescue the apoptosis of breast cancer cells induced by RBMS2." (PMID 35280673, 2022). "Therefore, we hypothesized that RBMS2 could sensitize breast cancer cells to DOX via inducing apoptosis regulated by BMF expression." (PMID 35280673, 2022). "In the present study, we examined the hypothesis that RBMS2 is a tumor suppressor in breast cancer." (PMID 30514345, 2018). "Moreover, RBMS2 was a favorable factor for breast cancer patients." (PMID 30514345, 2018). "In addition, our data showed that RBMS2 could induce breast cancer cells apoptosis." (PMID 35280673, 2022). "RBMS2 positively regulates the stability of P21 mRNA by binding to its 3’ -UTR and therefore inhibits the proliferation of breast cancer cells." (PMID 34804951, 2021). "RBMS2 was noted to stabilize mRNAs in breast cancer and lung cancer, whereas no corresponding research has been conducted in GC." (PMID 39719596, 2024). "Here, our study first reported that RBMS2 could induce apoptosis and increase DOX sensitivity by elevating BMF expression in breast cancer cells." (PMID 35280673, 2022). "In our study, we elucidated that RBMS2, together with BMF, could enhance apoptosis of breast cancer cells to promote the sensitivity to DOX." (PMID 35280673, 2022). "Migration and invasion assays didn’t show RBMS2 affect migration and invasion of breast cancer (data not shown)." (PMID 30514345, 2018). "We found RBMS2, RBMS3, RBMXL2 were the significantly differently expressed RBMs in breast cancer." (PMID 30514345, 2018). "Our previous study has illustrated that RBMS2 could act as a tumor suppressor and enhance the expression of P21 mRNA via directly binding to its AU-rich element (AREs) of 3′-untranslated region (3′-UTR) in breast cancer." (PMID 35280673, 2022). "Nevertheless, RBMS2-BMF axis could not sensitize breast cancer cells to 5-FU or cisplatin." (PMID 35280673, 2022).
lung carcinoma (2 papers, 2023 to 2024). "Investigations into different types of cancers such as lung cancer, gastric cancer, and hepatocellular carcinoma have reported a downregulation of RBMS2." (PMID 38058408, 2023).
Alzheimer disease (1 paper, 2025). A progressive, neurodegenerative disease characterized by loss of function and death of nerve cells in several areas of the brain leading to loss of cognitive function such as memory and language. "Single-cell validation confirmed vascular-endothelial dysfunction, with LAMC1, RBMS2 and TMOD3 upregulated in endothelial cells from female APOE ε4 Alzheimer’s disease brains." (PMID 41409615, 2025).
endothelial dysfunction (1 paper, 2025). In vascular diseases, endothelial dysfunction is a systemic pathological state of the endothelium (the inner lining of blood vessels) and can be broadly defined as an imbalance between vasodilating and vasoconstricting substances produced by (or acting on) the endothelium. "LAMC1, RBMS2, TMOD3, and LRP10 were suggested as key drivers of AD progression associated with endothelial dysfunction." (PMID 41409615, 2025).
tauopathy (1 paper, 2025). Neurodegenerative disorders involving deposition of abnormal tau protein isoforms (tau proteins) in neurons and glial cells in the brain. "APOE ε4 amplifies tau pathology via hub genes: In P301S tauopathy mice, female APOE ε4 boosted expression of Lrp10, Ltbp2, Lamc1, and Rbms2, revealing a potential link to the acceleration of tau-driven neurodegeneration." (PMID 41409615, 2025).
tumor (6 papers, 2018 to 2024). "Our research delves into the implications of RNA binding motif, single stranded interacting protein 2 (RBMS2) in kidney renal clear cell carcinoma (ccRCC), contributing to the growing body of evidence that underlines the tumor-suppressive role of RBMS2." (PMID 38058408, 2023). "RNA binding motif, single stranded interacting protein 2 (RBMS2), a gene commonly linked with tumor-suppressive properties, is the focus of our study." (PMID 38058408, 2023). "This research delves into the implications of the RNA binding motif, single stranded interacting protein 2 (RBMS2)—a gene associated with tumor-suppressing functions—in the context of kidney renal clear cell carcinoma (ccRCC)." (PMID 38058408, 2023). "In contrast to the findings regarding LINC01094, RBMS2 was found to have obvious tumor-suppressive effects in subsequent functional experiments in vitro." (PMID 39719596, 2024). "Significant differences in RBMS2 expression between tumor tissues and adjacent normal tissues were found by qRT-PCR and western blotting." (PMID 39719596, 2024). "Our findings are in line with previous research that has underscored the tumor-suppressive role of RBMS2 in various malignancies." (PMID 38058408, 2023). "In this study, we also shed light on these issues by investigating the role of RBMS2 in ccRCC and its relationship with the tumor microenvironment." (PMID 38058408, 2023). "In this context, we analyze the relationship between RBMS2 expression and immune infiltration in the tumor microenvironment of ccRCC." (PMID 38058408, 2023). "Second, while our in vitro experiments have demonstrated the tumor-suppressive role of RBMS2 in ccRCC, further in vivo experiments and mechanistic studies are required to comprehensively understand the biological function of RBMS2 in ccRCC." (PMID 38058408, 2023). "Collectively, our results underscore the tumor-inhibiting role of RBMS2 in ccRCC and spotlight its potential as a prognostic marker and therapeutic intervention target." (PMID 38058408, 2023). "It was previously found that two other RBMs, RBM38 and RBMS2 acted as tumor suppressor in breast cancers." (PMID 33145401, 2020). "Six weeks later, tumor weights in RBMS2 overexpression group were significantly lower than that of control group, which indicates RBMS2 inhibited tumor proliferation in vivo." (PMID 30514345, 2018). "Additionally, our research has unearthed links between RBMS2 and immune infiltration within the ccRCC tumor microenvironment." (PMID 38058408, 2023). "Additionally, our study has shed light on the interaction between RBMS2 expression and immune infiltration in the ccRCC tumor microenvironment, hinting at a role for RBMS2 in modulating the tumor immune microenvironment." (PMID 38058408, 2023). "Furthermore, our in vitro experiments provide biological evidence for the tumor-suppressive role of RBMS2 in ccRCC." (PMID 38058408, 2023). "Cellular experiments were undertaken to examine the tumor-suppressing role of RBMS2 in ccRCC." (PMID 38058408, 2023). "Importantly, we have also uncovered correlations between RBMS2 expression and immune infiltration in ccRCC, suggesting a potential role of RBMS2 in modulating the tumor immune microenvironment." (PMID 38058408, 2023). "Unraveling the molecular mechanisms underpinning the tumor-suppressive role of RBMS2 in ccRCC could provide novel insights into the pathogenesis of ccRCC." (PMID 38058408, 2023). "In vitro experiments further reinforce the tumor-inhibitory role of RBMS2 in ccRCC." (PMID 38058408, 2023). "Tumor volume of RBMS2 overexpression group increased slower than that of control group." (PMID 30514345, 2018). "Additionally, as our study suggests a potential role of RBMS2 in modulating the tumor immune microenvironment, it would be worthwhile to investigate whether RBMS2 could serve as a target for immunotherapy." (PMID 38058408, 2023).
tumor (continued). "RNA binding motif single stranded interacting protein 2 (RBMS2), an RBP, has been considered to be a tumor suppressor in several cancers." (PMID 35280673, 2022).
cancer (5 papers, 2011 to 2025). A tumor composed of atypical neoplastic, often pleomorphic cells that invade other tissues. "Alterations or disruptions in the normal functioning of RBMS2 have been found to be associated with the development of various types of cancers, underlining its crucial role in maintaining the delicate balance of cellular homeostasis." (PMID 38058408, 2023). "This diminished expression of RBMS2 is seen to contribute to the initiation and progression of these cancers, thereby establishing a link between RBMS2 downregulation and oncogenesis." (PMID 38058408, 2023). "Our research extends these findings to ccRCC, suggesting a broad implication of RBMS2 in cancer biology." (PMID 38058408, 2023). "Rbms2 is a tumor suppressor gene that inhibits cell proliferation by positively regulating the stability of P21, mediates cell apoptosis, and enhancing sensitivity to several cancer treatments." (PMID 39962271, 2025). "Within the very few genes showing under-expression in ERG-negative carcinomas with an even more marked fold-decrease in ERG-positive lesions, RBMS2 (nucleic acid binding protein) displayed a massive fold-change reduction, which we set out to validate." (PMID 21814574, 2011).
RBMS2 also shares sentences with these, for which no sentence is quoted: prostate carcinoma (2 papers); bladder carcinoma (1); gastric cancer (1); leukemia (1).